RN7SL658P (RNA, 7SL, cytoplasmic 658, pseudogene)
Gene: Miscellaneous RNA gene on chromosome X (16,539,137 to 16,539,439, reverse strand). Ensembl gene ENSG00000239333.
Homologues: Orthologues: chimpanzee Metazoa_SRP (99% identical), macaque Metazoa_SRP (92% identical). Paralogues in human: RN7SL1 (82% identical), RN7SL3 (82% identical), RN7SL2 (82% identical), RN7SL126P (80% identical), RN7SL679P (80% identical), RN7SL220P (79% identical), RN7SL597P (79% identical), RN7SL357P (79% identical), RN7SL709P (79% identical), RN7SL416P (78% identical), RN7SL448P (78% identical), RN7SL113P (78% identical), and 699 more.